PPY (pancreatic polypeptide)
Description:
[Pancreatic polypeptide]: Hormone secreted by pancreatic cells that acts as a regulator of pancreatic and gastrointestinal functions probably by signaling through the G protein-coupled receptor NPY4R2.
Synonyms: PH; PP; PNP
Tractability: Antibody: UniProt places it where antibodies can reach, with high confidence; its Gene Ontology location is reachable by antibodies, with high confidence; UniProt predicts a signal peptide or a membrane-spanning region.
Gene: Protein-coding gene on chromosome 17 (43,940,804 to 43,944,144, reverse strand). Ensembl gene ENSG00000108849.
Subcellular location: Secreted
Pathways (Reactome):
Signal Transduction: G alpha (i) signalling events; Peptide ligand-binding receptors
Gene Ontology:
Molecular function: G protein-coupled receptor binding; protein binding; hormone activity; neuropeptide hormone activity; neuropeptide Y receptor binding
Biological process: feeding behavior; neuropeptide signaling pathway; protein secretion
Cellular component: extracellular region; cytoplasm
Genetic constraint (gnomAD): Loss-of-function variants: 6 observed, 8.99 expected, observed/expected ratio (o/e) 0.67, 90% interval 0.36 to 1.31. That is too few expected variants to judge how well the gene tolerates losing a copy. Missense variants: 109 observed, 121.45 expected, observed/expected ratio (o/e) 0.9, 90% interval 0.77 to 1.05. Synonymous variants: 58 observed, 54.52 expected, observed/expected ratio (o/e) 1.06, 90% interval 0.86 to 1.32.
Homologues: Orthologues: chimpanzee PPY (100% identical), macaque PPY (92% identical), rabbit PPY (80% identical), pig PPY (77% identical), dog PPY (75% identical), guinea pig Ppy (63% identical), mouse Ppy (61% identical), rat Ppy (61% identical). Paralogues in human: NPY (37% identical), PYY (31% identical).
Diseases named in the same sentence as PPY in open-access papers:
PPY is named in the same sentence as 58 diseases in open-access papers, as found by Europe PMC text mining. Sharing a sentence is not in itself a finding about the gene and the disease. The quoted sentences say what the papers report.
diabetes (15 papers, 2011 to 2024). "Furthermore, pancreatic inflammation leads to the decrease of islet cell mass leading to the loss of glucagon, insulin, and pancreatic polypeptide, which difficult the control of diabetes with large variations in blood glucose." (PMID 39030443, 2024). "Pancreatic polypeptide is also linked with diabetes and obesity and may provide a clue into the biological link between these conditions and AD." (PMID 22163278, 2011). "In addition to these associations, higher levels of insulin, gastric inhibitory polypeptide, and pancreatic polypeptide remained significantly associated with self-reported diabetes with a false discovery rate <5%, indicating that the assay was able to detect markers associated with diabetes." (PMID 28753646, 2017). "By counting anti-pancreatic polypeptide-labeled cells, there was an increase in the percentage of PP-cells as diabetes was induced." (PMID 39337311, 2024). "Pancreatic diabetes usually manifests as “brittle diabetes” with poor glucose control due to impaired insulin, glucagon and pancreatic polypeptide." (PMID 29212278, 2017). "The resolution of postoperative complications such as diabetes observed in some patients after pancreatoduodenectomy may be explained in part by the decrease in glucagon and pancreatic polypeptide release measured." (PMID 39430095, 2024). "Furthermore, we showed that the modified WB is applicable to other diabetes-associated peptide hormones: insulin analogs, glucagon, GLP-1s, somatostatins, ghrelins, and pancreatic polypeptide." (PMID 28761041, 2017). "As well as in this paper, Xen amplifies the effects of GIP on insulin, glucagon, and pancreatic polypeptide release during graded glucose infusions in humans without type 2 diabetes mellitus." (PMID 29466430, 2018). "Similarly, Xen infusion increased the postprandial pancreatic polypeptide response 6-fold in humans with normal glucose tolerance, impaired glucose tolerance, and type 2 diabetes mellitus without affecting ISRs or plasma glucagon levels." (PMID 29466430, 2018).
Obesity (7 papers, 2011 to 2023). Accumulation of substantial excess body fat. "According to one research article, the GG genotype of variant rs231472 in the PPY gene correlates with the risk of obesity in children in Korea." (PMID 36983642, 2023). "Due to the CNV and the role of NPY4R and its ligand pancreatic polypeptide in the regulation of food intake, this gene is a strong candidate for contribution to body weight variation and obesity." (PMID 31164119, 2019). "QTL for NVD was homologous with HSA 17q21 regions which contained many obesity candidate genes including PPY, PON1 and 2, GAST, PNMT, STAT3 and HCRT." (PMID 23977060, 2013). "In addition to GLP-1, pancreatic polypeptide (PP) and peptide YY (PYY)—peptides of gut origin affecting the gastrointestinal tract—have central anorexigenic effects (gut-brain peptides) and have been evaluated as possible treatments for obesity." (PMID 28820912, 2017).
type 2 diabetes (7 papers, 2017 to 2025). "Mapping of type 2 diabetes GWAS genes to specific cells also revealed that macrophages and delta cells had a higher number of differentially expressed type 2 diabetes risk genes than pancreatic polypeptide and alpha cells." (PMID 39508880, 2025). "Islets from control, autoantibody-positive, type 2 diabetes, and 11 of 16 type 1 diabetes donors contain the four islet cell types (α-, β-, δ-, and pancreatic polypeptide (PP) cells)." (PMID 32424134, 2020). "As the insulin tropic action of PPY is preserved in type 2 diabetic patients, this peptide was a candidate as a therapeutic agent for this disease." (PMID 28228865, 2017).
neuroendocrine tumors (6 papers, 2005 to 2025). "Tumors 2 and 7 had high levels of pancreatic polypeptide, and came from patients with only a diagnosis of neuroendocrine tumor." (PMID 15691381, 2005). "Current international MEN1 guidelines recommend annual biomarker screening of patients with MEN1, including chromogranin A (CgA) and pancreatic polypeptide (PP) screenings for diagnosis and follow-up of patients with gastroenteropancreatic neuroendocrine neoplasms (NENs)." (PMID 40455177, 2025). "Furthermore, immunohistochemical expression of progesterone receptor and pancreatic polypeptide were useful in distinguishing between GP and neuroendocrine tumor G1, even in small biopsy specimens." (PMID 30101131, 2018).
pancreatic neuroendocrine tumor (5 papers, 2019 to 2025). Pancreatic endocrine tumor, also known as pancreatic neuroendocrine tumor (PNET), describes a group of endocrine tumors originating in the pancreas that are usually indolent and benign, but may have the potential to be malignant. "In patients with multiple endocrine neoplasia type 1 (MEN1) followed up at ENETS centers of Excellence, chromogranin A (CgA) and pancreatic polypeptide (PP) are widely used screening tools for pancreatic neuroendocrine tumors (panNETs)." (PMID 40455177, 2025). "In the diagnosis of pancreatic NETs, the determination of CgA and pancreatic polypeptide is significantly useful." (PMID 36289922, 2022). "We report a patient with multiple endocrine neoplasia type 1 with pancreatic polypeptide (PP) secreting subcentimeter pancreatic neuroendocrine tumors (pNETs) treated with octreotide and review the current literature that pertains to the management of these patients." (PMID 31183223, 2019). "Functioning pancreatic neuroendocrine tumors (pNETs) that express pancreatic polypeptide—PPomas—do not yet have a pathognomonic clinical syndrome associated with them due to their overall rarity and diverse symptoms." (PMID 34118524, 2021).
rectal cancer (5 papers, 2021 to 2024). A primary or metastatic malignant neoplasm that affects the rectum. "In conclusion, we identified two markers (FGF-21 and PPY) that were associated with colon and rectal cancer respectively, suggesting a potential of biomarkers to discriminate between different subtypes of colorectal cancer." (PMID 33664295, 2021). "Similarly, Harlid and colleagues have identified that fibroblast growth factor 21 (FGF-21) and pancreatic prohormone (PPY) are associated with the risk of colon and rectal cancers, respectively, in plasma samples from asymptomatic patients and in a pre-diagnostic setting." (PMID 38396959, 2024). "(2021) showed that fibroblast growth factor 21 (FGF21) was associated with early, but not late stages of colon cancer, while pancreatic prohormone (PPY) was a promising biomarker for rectal cancer detection." (PMID 37228491, 2023). "In the subgroup analyses based on tumor site, FGF-21 (OR: 1.23, 95% CI 1.03–1.47) and 5’NT (OR: 0.86, 95% CI 0.79–0.99), were associated with colon but not rectal cancer, whereas PPY (OR: 1.47, 95% CI 1.12–1.92) was associated with rectal but not colon cancer." (PMID 33664295, 2021). "Despite being potentially predictive and possibly related to colorectal cancer etiology, neither FGF-21 nor PPY would be useful as standalone biomarkers of colon or rectal cancer." (PMID 33664295, 2021). "However, neither FGF21 nor PPY could be used as stand-alone biomarkers for colon or rectal cancer but might be used as an efficient tool to discriminate between different subtypes of CRC." (PMID 37228491, 2023).
Anxiety (4 papers, 2008 to 2020). Intense feelings of nervousness, tension, or panic often arise in response to interpersonal stresses. "For instance, postprandial release of pancreatic polypeptide (PP) reduced food intake and altered stress‐induced motor activity and anxiety by activating central Y4 receptors." (PMID 26844810, 2016). "The NPY family of neuropeptides, including NPY, peptide YY (PYY), and pancreatic polypeptide (PP), has been shown to elicit diverse biological functions including hypothalamic control of food intake, anxiety and sedation." (PMID 18836554, 2008). "After a 4 h fast, appetite perceptions, GI symptoms, state anxiety, and plasma acyl-ghrelin, cholecystokinin (CCK), peptide tyrosine tyrosine (PYY) and pancreatic polypeptide (PP) concentrations were assessed at baseline and in response to a mixed-nutrient test-meal (479 kcal)." (PMID 30597915, 2018).
Hypoglycemia (4 papers, 2014 to 2023). A decreased concentration of glucose in the blood. "In a study evaluating altered vagal and intestinal mechanosensory function in patients with chronic unidentified dyspepsia, the pancreatic polypeptide response to insulin induced hypoglycemia had been shown to diminished." (PMID 29914168, 2018). "Hypoglycemia resulted in significantly reduced epinephrine, norepinephrine, glucagon, growth hormone, pancreatic polypeptide, and hepatic glucose production responses in females as compared to males." (PMID 25964778, 2015). "Our studies showed that hypoglycemia following hyperglycemia in ferrets produces increases in glucagon and pancreatic polypeptide, similar to that observed in human studies." (PMID 24594704, 2014). "Hypoglycemia induced a rapid diminishment of insulin, as well as a rise in glucagon and pancreatic polypeptide levels." (PMID 24594704, 2014). "Pancreatic polypeptide levels were significantly lower in patients with post-bariatric hypoglycaemia vs the non-surgical control group (median [IQR]: 24.7 [10.9, 38.7] pmol/l vs 238.7 [186.3, 288.9] pmol/l) (p=0.005)." (PMID 36648553, 2023).
pancreatic cancer (4 papers, 2020 to 2025). "In cases of chronic pancreatitis, pancreatic cancer, and pancreatic resection, pancreatic polypeptide (PP) is also deficient." (PMID 36672448, 2023). "According to the qRT‐PCR analysis of PPY expression in pancreatic cancer cell lines, PANC‐1 cells exhibiting high levels of PPY, BxPC‐3 cells with low levels of PPY, and murine pancreatic cancer cell line Panc02 were selected for further investigation." (PMID 40162859, 2025). "While the remaining two genes, HCAR3 (Hydroxy-Carboxylic Acid Receptor 3) and PPY (Pancreatic Polypeptide), have not previously been linked with pancreatic cancer prognosis yet, this study provides a theoretical basis for investigating their potential role in pancreatic cancer." (PMID 32724299, 2020). "The prognosis significance, biological functions and molecular mechanisms of the factors, including HCAR3, PPY, RFWD2, WSPAR and Amcinonide, should be investigated alone and in combination to facilitate the translational research of pancreatic cancer." (PMID 32724299, 2020).
type 1 diabetes (4 papers, 2020 to 2024). "The expression of PPY significantly correlated with Aminoacyl-tRNA biosynthesis, Hedgehog signaling pathway, Basal cell carcinoma, Cell cycle, Ubiquitin mediated proteolysis, Tyrosine metabolism, Type I diabetes mellitus, Allograft rejection, Asthma, Graft-versus-host disease." (PMID 38239411, 2023).
carcinoids (3 papers, 2014 to 2024). "Interestingly, peptides typical of the neuroendocrine differentiation of pancreatic tumors such as glucagon and pancreatic polypeptide were expressed in 80% and 100% of the strumal carcinoids tested." (PMID 35528006, 2022).
cognitive disorder (3 papers, 2015 to 2026). A disease affects cognitive processes. "Conditional logistic regression models for association of pancreatic polypeptide with mild cognitive impairment." (PMID 26441635, 2015).
gastrinoma (3 papers, 2019 to 2022). "Insulinomas and gastrinomas are the most common functioning panNETs, whilst glucagonoma, vasointestinal peptide (VIP)oma, pancreatic polypeptide (PP)oma, somatostatinoma and adrenocorticotropic hormone (ACTH secreting panNETs are rarer." (PMID 35156246, 2022). "The process of tumour detection involved biochemical screening tests including gastrin, glucose, insulin, chromogranin-A, pancreatic polypeptide, glucagon, vasointestinal polypeptide, prolactin and IGF-1 to assess for gastrinoma, insulinoma, enteropancreatic and anterior pituitary tumours." (PMID 31797261, 2020).
insulinoma (3 papers, 2005 to 2020). "Among the tumors, all 3 insulinomas clustered together, separate from the VIP-oma, the glucagonoma and the PP-omas (pancreatic polypeptide producing tumors)." (PMID 15691381, 2005).
multiple endocrine neoplasia type 1 (3 papers, 2019 to 2025). An autosomal dominant tumor predisposition syndrome caused by pathogenic variants in the MEN1 gene, characterized by an increased risk of tumors of the parathyroid glands, pituitary gland, and foregut neuroendocrine tumors (most commonly pancreatic islet cells). "PPY is a marker of some pancreatic tumors including pancreatic polypeptide-secreting tumor of the distal pancreas (PPoma) and Multiple endocrine neoplasia type 1 (MEN1) both of which are characterized by high serum levels of PPY29." (PMID 33664295, 2021).
anorexia nervosa (2 papers, 2015 to 2022). A disorder most often seen in adolescent females characterized by a refusal to maintain a minimally normal body weight, an intense fear of gaining weight, a disturbance in body image, and, in postmenarcheal females, the development of amenorrhea. "Pancreatic polypeptide, which was elevated in patients, has been linked to anorexia nervosa, and another member of the pancreatic polypeptide family, peptide YY, was (marginally) positively related to depressive symptoms in older adults." (PMID 32779563, 2022).
Insulin resistance (2 papers, 2019 to 2024). Increased resistance towards insulin, that is, diminished effectiveness of insulin in reducing blood glucose levels. "Insulin resistance in such patients is most often of hepatic origin and occurs in long-term CP due to a decrease in the number of PP cells and, thus, a decrease in the synthesis of pancreatic polypeptide." (PMID 39896151, 2024). "Minor criteria include impaired B cell function, low levels of fat-soluble vitamins (A, D, E, and K), lack of excessive insulin resistance, and impaired incretin release or pancreatic polypeptide secretion." (PMID 31687406, 2019).
lung carcinoids (2 papers, 2023 to 2024). "Several hormones, including serotonin (84%), pancreatic polypeptide, gastrin, gastrin-releasing peptide, calcitonin, ACTH, and growth-hormone-releasing hormone often show positive immunostaining in lung carcinoids; multiple hormones may be found in the same tumor." (PMID 38001701, 2023).
allergic asthma (1 paper, 2014). A asthma with a basis in a pathological type I hypersensitivity reaction. "We demonstrated that PPY has inhibitory effect on allergic asthma through blocking the activation of the NF-kB and ERK1/2 signaling pathways." (PMID 24489937, 2014).
autonomic dysfunction (1 paper, 2018). "Abnormal gastrointestinal peptide release due to autonomic dysfunction (including pancreatic polypeptide, motilin) causes additional motility and secretory dysfunctions that result in abnormal carbohydrate absorption." (PMID 29725320, 2018).
breast carcinoma (1 paper, 2019). "In this prospective case-control study nested within the Mano a Mano Cohort Study, we assessed the risk of breast cancer with regard to plasma levels of c-peptide, gastric inhibitory polypeptide, insulin, leptin, monocyte chemoattractant protein-1, pancreatic polypeptide, and peptide YY." (PMID 31292496, 2019).
colitis (1 paper, 2022). Inflammation of the colon. "Additionally, the other two peptides from same family, neuropeptide Y (NPY) and pancreatic polypeptide, bind to the same receptors as PYY and may also play some unknown functional roles in the experimental colitis mouse model." (PMID 35443853, 2022).
colorectal cancer (1 paper, 2021). A primary or metastatic malignant neoplasm that affects the colon or rectum. "Few studies have specifically examined levels of PPY in colorectal cancer patients compared to healthy controls." (PMID 33664295, 2021).
Crohn disease (1 paper, 2022). A gastrointestinal disorder characterized by chronic inflammation involving all layers of the intestinal wall, noncaseating granulomas affecting the intestinal wall and regional lymph nodes, and transmural fibrosis. "Related papers have shown that the amount of colonic PYY and pancreatic polypeptide (PP), as well as the number of oxyntomodulin-producing EECs, were decreased in patients with Crohn’s disease." (PMID 35050153, 2022).
cyst (1 paper, 2019). A sac-like closed membranous structure that may be empty or contain fluid or amorphous material. "The spermatid heads were labeled with ProtamineA-GFP and cyst cell membrane was labeled with PpY>mCD8-RFP in both the control (ProtA-GFP/UAS-Dicer; PpY-Gal4>UAS-mCD8-RFP/+) and dlg1 RNAi (ProtA-GFP/UAS-dsDlg1; PpY-Gal4>UAS-mCD8-RFP/+) backgrounds." (PMID 30635267, 2019). "Although PpY-Gal4 is expressed in the SCCs from the post-mitotic stages, PpY-Gal4-mediated expression of dsDlg1 eliminates the protein from the SCCs only at the last stage of spermatid maturation, when the cyst enters the TE, and leads to premature spermatid release inside the testis." (PMID 30635267, 2019).
glioblastoma (1 paper, 2025). The most malignant astrocytic tumor (WHO grade IV). "PPY, typically associated with neuroendocrine signaling, emerged as a significant prognostic indicator in glioblastoma." (PMID 40725410, 2025). "The neuropeptide-related genes, including PPY and members of the NPY family (e.g., NPY, NPY1R, NPY2R, NPY4R, NPY5R, PYY), form a distinct cluster characterized by strong co-expression and shared pathway interactions, indicating a potential role in neuroendocrine signaling relevant to glioblastoma." (PMID 40725410, 2025).
Hyponatremia (1 paper, 2014). An abnormally decreased sodium concentration in the blood. "Cases with symptoms of ghrelin secretion of insulin, of pancreatic polypeptide, of paraneoplastic sensory neuropathy, or of hyponatremia have been described." (PMID 25328753, 2014).